SLC7A11 (solute carrier family 7 member 11)
Diseases named in the same sentence as SLC7A11 in open-access papers (continued):
Sharing a sentence is not in itself a finding about the gene and the disease.
tumor (continued). "Moreover, data from The Cancer Genome Atlas (TCGA) were utilized to investigate the effect of SLC7A11 expression on the tumor microenvironment (TME), the tumor mutation burden (TMB), and the drug sensitivity." (PMID 40978058, 2025). "Core regulators of ferroptosis, such as GPX4 and SLC7A11, are highly expressed in various GI tumors and are associated with poor prognosis; inhibiting their function can effectively trigger lipid peroxidation-mediated death in tumor cells." (PMID 41201667, 2025). "Its expression is linked with immune cell infiltration in the tumor microenvironment, suggesting that targeting SLC7A11 could be promising for ACC treatment." (PMID 41223189, 2025). "Tumor inhibition by BRCA1-associated protein 1 (BAP1) could be achieved in part by inhibiting SLC7A11 and thereby promoting ferroptosis." (PMID 40498062, 2025). "In addition, overexpression of SLC7A11 is associated with a poor prognosis in various cancers, suggesting its important role in tumor progression and drug resistance." (PMID 39742309, 2024). "High levels of ACSL4 and SLC7A11 in CCA sera were both significantly associated with advanced tumor stages and abnormal liver function test results, indicating that they could be used as a reliable prognostic biomarker panel in patients with CCA." (PMID 39335604, 2024). "Significant associations were also found between elevated SLC7A11 levels and the tumor growth type." (PMID 39335604, 2024). "Additionally, this phenomenon has been replicated in vivo, within a tumor microenvironment, where the metabolic reprogramming associated with altered SLC7A11 expression was evident." (PMID 39040097, 2024). "In addition, high levels of ACSL4 and SLC7A11 in CCA sera were significantly associated with advanced tumor staging, poorer prognosis parameters, and a short survival time." (PMID 39335604, 2024). "Tumor cells usually need to highly express the SLC7A11 protein to recruit additional cystine for the synthesis of reduced glutathione, which balances the oxidation caused by the highly active metabolism of tumor cells." (PMID 39091494, 2024). "SLC7A11 expression causes cellular ferroptosis or enhances tumor killing by immune cells by affecting oxidative status or nutrient and energy metabolism in the tumor microenvironment (TME)." (PMID 39040097, 2024). "Notably, the research highlights an association between the overexpression of SLC7A11 and increased tumor growth, suggesting a potential link between its promotion of tumorigenesis and the inhibition of ferroptosis." (PMID 38510357, 2024). "There was also a positive association between elevated SLC7A11 levels and tumor growth type." (PMID 39335604, 2024). "SLC7A11 expression is associated with more unfavorable prognosis and more advanced tumor stage." (PMID 36874967, 2023). "And SLC7A11 expression is also associated with more advanced tumor stage." (PMID 36874967, 2023). "For example, tumor cells can maintain high levels of glutathione by upregulating the expression of the catalytic subunit SLC7A11 of the Xc− system to counteract the oxidative stress caused by the increased rate of their own metabolism (Koppula, Zhuang & Gan, 2021)." (PMID 36874967, 2023). "These suggest that SLC7A11 overexpression is positively associated with tumour progression." (PMID 38273826, 2023). "The tumour mutation burden and neoantigen level are positively associated with SLC7A11 expression." (PMID 37378426, 2023).
tumor (continued). "Finally, the key R packages “corrplot”, “maftools”, and “oncoPredict” were utilized for conducting correlation analysis among SLC7A11 expression levels, immune checkpoint-related genes, tumor mutation burden, and drug sensitivity." (PMID 37919768, 2023). "Thus, loss of STAT1 in tumor cells abrogates interferon gamma-mediated downregulation of SLC7A11 while reversing RSL3-induced lipid peroxidation and ferroptosis." (PMID 37488128, 2023). "The nutrient dependence caused by SLC7A11 enhances ferroptosis in tumor cells, and this pathway may solve chemoresistance in OS." (PMID 37329384, 2023). "The immunohistochemistry analysis of the tumor tissue showed that the mean area that stained positively for Ki-67, which is associated with proliferation, and SLC7A11 and GPX4, which are associated with anti-ferroptosis, were smaller under GRh3 treatment than in the control samples." (PMID 37092860, 2023). "Collectively, overexpression of SLC7A11 was shown to cause tumor cell dependence on both glutamine and glucose, although the mechanisms for this dependence may vary." (PMID 37298344, 2023). "In addition, we performed a correlation analysis for SLC7A11 expression and tumour mutational burden and immune checkpoint-related genes and assessed drug sensitivity based on SLC7A11 expression." (PMID 37919768, 2023). "Furthermore, SLC7A11 overexpression in human HCC is strongly linked with worse tumor differentiation, a higher tumor-nodule-metastasis stage, as well as a poor prognosis." (PMID 37488128, 2023). "Solute carrier family 7 member 11 (SLC7A11; also known as xCT), a key component of the cystine/glutamate antiporter, is essential for the maintenance of cellular redox status and the regulation of tumor-associated ferroptosis." (PMID 36338517, 2022). "In the case of cell proliferation, invasion and drug resistance caused by appropriate ROS, cystine supplementation, or SLC7A11 activation could rebalance redox and reduce the effect of ROS on the malignancy of tumours." (PMID 35804831, 2022). "xCT encoded by SLC7A11 is essential for cancer cell survival and tumor formation in vivo." (PMID 33401748, 2021). "Importantly, cancer-associated BAP1 mutations are defective in SLC7A11 regulation and ferroptosis, suggesting that SLC7A11-mediated ferroptosis has a role in the tumor-suppressive function of BAP1." (PMID 33499222, 2021). "IFN-γ derived from immunotherapy-activated CD8+ T cells synergizing with radiotherapy-activated ataxia-telangiectasia mutated (ATM) suppresses SLC7A11, to induce cystine uptake, enhance tumor lipid oxidation and ferroptosis in human fibrosarcoma and melanoma cells." (PMID 34858857, 2021). "Previous studies have validated that IFNG could suppress SLC7A11, causing reduced cystine uptake, enhanced tumor lipid oxidation and ferroptosis, and improved tumor control." (PMID 34885178, 2021). "Overexpression of SLC7A11 is also associated with a cancer stem-cell-like phenotype and thus may additionally contribute to tumor progression." (PMID 33171923, 2020). "To investigate the relationship between the FX-mediated suppression of tumor development and ferroptosis, we conducted an immunohistochemistry (IHC) analysis to assess the expression of vital ferroptosis-associated targets, including SLC7A11 and GPX4 in tumor tissues." (PMID 40137309, 2025). "In addition, closely correlation between SLC7A11 and advanced stage indicated that tumor progression mediated by SLC7A11 might contribute to SLC7A11 caused worse prognosis." (PMID 36874967, 2023).
tumor (continued). "Thus, the immune chemokines CXCL8, CXCL3, and CCL20, which are positively associated with SLC7A11, have SLC7A11-like functions in the development of tumours and provide evidence of association at the tumour immune microenvironment level for poor prognosis in ACC patients with SLC7A11high." (PMID 37919768, 2023). "Therefore, the susceptibility of SLC7A11-high cancer cells to oxidative stress may be more pronounced in metastasizing cancer cells than in primary tumor cells." (PMID 37339981, 2023). "Thus, SLC7A11 expression is strongly associated with the tumour immune microenvironment." (PMID 37919768, 2023). "Therefore, in such cancers that SLC7A11 is negatively associated with immune/stromal score, SLC7A11 may be expressed more in tumor cells instead of immune/stromal cells." (PMID 34938318, 2021). "The regulatory networks linking ferroptosis and stemness, such as those mediated by NRF2, SLC7A11, and iron metabolism genes, require further elucidation to decipher the multi-target mechanisms of these compounds within the tumor microenvironment (TME)." (PMID 41601687, 2026). "OTUB1 suppresses ferroptosis and maintains tumor cell survival by deubiquitinating and stabilizing key proteins like SLC7A11, GPX4, and p62." (PMID 42086528, 2026). "Cystine, a crucial substrate, is primarily transported into tumor cells by SLC7A11 protein within the tumor microenvironment." (PMID 41362671, 2026). "APC membrane recruitment protein 1 (AMER1), another tumor suppressor, facilitates ferroptosis by degrading both SLC7A11 and ferritin light chain in colorectal cancer cells." (PMID 41596341, 2026). "A study found that immune checkpoint inhibitors activate and induce CD8+ T cells to secrete interferon‐gamma (IFN‐γ), which negatively regulates the expression of the Xc system components SLC3A2 and SLC7A11 on the surface of tumor cells." (PMID 41560416, 2026). "SLC7A11 mediates SLC16A1-driven tumor cell proliferation, ferroptosis resistance, and tumorigenesis." (PMID 42065048, 2026). "This reveals a novel mechanism underlying emodin's anti-tumor activity and highlights its promise as a therapeutic agent for HCC, particularly in SLC7A11-overexpressing subtypes, with potential to enhance combination therapies and overcome drug resistance." (PMID 41959927, 2026). "In various cancers, SLC7A11 is often overexpressed, contributing to tumor growth and survival by inhibiting ferroptosis." (PMID 40535572, 2025). "Correlation analysis of CAV1 molecules and SLC7A11 showed a significant positive correlation between them, with correlation coefficients of 0.69, 0.61, and 0.88 in the three tumor models, respectively." (PMID 40180904, 2025). "HRD1 inhibits tumor proliferation and metastasis by promoting the ubiquitination and degradation of SLC7A11." (PMID 40539051, 2025). "For example, in HCC cells and xenograft tumor models in nude mice, curcumin significantly downregulates the expression of SLC7A11, GPX4, GSS, and FTH1, while upregulating ACSL4 and PTGS2, thereby altering the ferroptosis-sensitive phenotype." (PMID 41515171, 2025). "Researchers found that valtrate (Val) dramatically reduces tumor size and weight in xenograft tumor models by raising cleaved caspase-3 expression and lowering SLC7A11 and GPX4 expression." (PMID 40191731, 2025). "Together, our data indicate that inhibition of ER stress response enhances GLUT inhibitors‐induced disulfidptosis and subsequent tumor suppression in SLC7A11‐high tumor cells." (PMID 39739602, 2025). "Up-regulation or activation of SLC7A11 can increase the fitness of cancer cells, leading to the lasting progression of a tumor in an unfavorable environment." (PMID 39569390, 2025).
tumor (continued). "For instance, miR-148a-3p has been recognized as a tumor suppressor that negatively influences SLC7A11, thereby promoting ferroptosis in colorectal cancer cells." (PMID 40535572, 2025). "In lung and liver cancers, high SLC7A11 expression promotes tumor growth by suppressing ferroptosis." (PMID 40520902, 2025). "Collectively, these findings suggested that SNHG12-mediated SLC7A11 upregulation promoted the adaptation of NSCLC cells to TAM2 polarization in the tumor microenvironment." (PMID 40417819, 2025). "LINC UC.339 inhibits ferroptosis and promotes tumor proliferation in lung cancer cells through the UC.339/miR-339/SLC7A11 axis." (PMID 40191204, 2025). "The expression of SLC7A11 is meticulously regulated by a range of oncogenes and tumor suppressors, highlighting its crucial role in tumor biology, especially regarding cancer progression and the development of resistance to treatments." (PMID 40535572, 2025). "Upregulation of ALKBH5 promotes ferroptosis in NSCLC cells by decreasing SLC7A11 expression, thereby inhibiting tumor invasion and metastasis." (PMID 40740874, 2025). "In vivo experiments on mice also demonstrated that GLUT inhibitors significantly inhibited tumor growth and induced aberrant disulfide cross-linking of actin cytoskeletal proteins in SLC7A11-high." (PMID 40303412, 2025). "Inactivated RUNX3 cannot effectively transactivate its downstream targets, leading to the suppression of SLC7A11-mediated ferroptosis and promoting malignant tumor progression." (PMID 41201667, 2025). "It inhibited tumour growth by promoting ferroptosis via mTOR/S6KP70‐dependent mechanisms, suppressing SLC7A11 expression, causing lipid peroxidation, and decreasing GSH levels." (PMID 40916076, 2025). "IFN‐γ derived from CD8+ T cells can increase the tumour vulnerability to radiotherapy and immunotherapy by synergistic repressing tumour SLC7A11 expression to promote tumour cell ferroptosis." (PMID 40045458, 2025). "CD8(+) T cells are very important in cancer immunotherapy because they produce IFNγ, which activates the STAT1 signalling pathway, inhibits SLC7A11 expression and induces ferroptosis in tumour cells." (PMID 39865544, 2025). "Once it was reported that in oral squamous carcinoma (OSCC) METTL3 enhanced the stability of SLC7A11 and regulated the proliferation, invasive and migrative ability of tumor cells, and thus promoted the progression of OSCC." (PMID 39799112, 2025). "Studies have demonstrated that glucose transporter inhibitors (e.g. BAY-876) can induce disulfidptosis by obstructing glucose uptake, which leads to NADPH depletion in tumor cells with elevated SLC7A11 expression." (PMID 41185600, 2025). "Due to the high expression of SLC7A11, tumor cells outcompete T cells for cystine uptake, a mechanism that promotes CD36-mediated CD8 + T cells." (PMID 41326356, 2025). "In tumor therapy, engineered magnetic microspheres induce TAMs polarization to the M1 phenotype through the TLR4/NF-κB pathway, which reduces the expression of SLC7A11 in tumor cells and thus increases ferroptosis sensitivity." (PMID 40535125, 2025). "Conversely, in cervical squamous cell carcinoma (CSCC), HOXA5-mediated transcriptional downregulation of the ferroptosis suppressor SLC7A11 significantly increases ferroptosis sensitivity and promotes tumor cell death." (PMID 41479924, 2025). "Experimental evidence shows that STAT1 knockout in tumor cells blocks IFNγ‐induced SLC7A11 downregulation and significantly reduces RSL3‐triggered LPO and ferroptosis susceptibility." (PMID 40919133, 2025). "Earlier studies indicated that SLC7A11 predominantly functioned as an amino acid transporter, regulating intracellular metabolism and influencing tumor immune responses." (PMID 39820491, 2025).
tumor (continued). "Based on tumor grade, SLC7A11 expression was also elevated in patients with grade 1, grade 2, and grade 3 HNSCC compared to normal tissues." (PMID 40378782, 2025). "In the KPFSR model, tamoxifen-induced systemic deletion of Slc7a11 triggered tumor-selective ferroptosis and significantly inhibited tumor growth." (PMID 41293165, 2025). "For example, IFNγ released by CD8+ T cells suppresses SLC7A11 expression in tumor cells, linking immune surveillance to ferroptotic clearance—a mechanism exploited in ICI therapies." (PMID 40919133, 2025). "This suppression was partially reversed by WDR74 overexpression, while SLC7A11 knockdown mitigated the tumor-promoting effects." (PMID 40959275, 2025). "IFN-γ derived from immunotherapy-activated CD8+ T cells and radiotherapy-activated ATM independently inhibits SLC7A11, ultimately leading to reduced cystine uptake, elevated tumor lipid peroxidation levels, and the occurrence of ferroptosis." (PMID 40260246, 2025). "Here, we showed that inflammatory signaling-induced lncRNA SLC7A11AR promoted tumor growth via interacting with miR-150-5p, thus increasing SLC7A11 expression and reducing ferroptosis." (PMID 40765833, 2025). "In vivo xenograft models further revealed that SLC7A11 knockdown inhibited tumor growth and metastasis, corroborated by histological analyses." (PMID 41030277, 2025). "SLC7A11 plays a pivotal role in tumour development by facilitating cystine import to enhance glutathione synthesis and counteract oxidative stress." (PMID 39354653, 2025). "This protein significantly suppresses target gene expression by regulating histone H2A deubiquitination at the SLC7A11 promoter region, thereby activating ferroptosis for tumor suppression." (PMID 40919133, 2025). "For example, CD8+ T lymphocytes suppress SLC7A11 in tumor cells and secrete IFN-γ to induce ferroptosis." (PMID 40822970, 2025). "By orchestrating the expression of detoxifying enzymes (e.g., GPX4 and HO-1), cystine transporters (e.g., SLC7A11), iron regulators, and immune modulators (e.g., PD-L1), Nrf2 enables tumor cells to adapt to ferroptotic stress." (PMID 40867889, 2025). "In the tumor microenvironment, where oxidative stress and nutrient deprivation are prevalent, upregulation of SLC7A11 facilitates increased cysteine uptake, thereby enhancing glutathione levels and providing a survival advantage against oxidative damage." (PMID 41030277, 2025). "To assess ferroptosis levels in tumor tissues, we performed IHC staining for SLC7A11 and 4-HNE, and measured lipid peroxidation, MDA levels, and GSH content." (PMID 40959275, 2025). "In contrast, CD44v is mainly considered an activator that regulates various cell membrane proteins, including SLC7A11, to support tumor growth and therapy resistance." (PMID 40259468, 2025). "In contrast, SCFAs (such as butyrate) tend to promote ferroptosis and suppress tumor growth by downregulating SLC7A11 and GPX4 expression." (PMID 41293165, 2025). "Tumor molecular markers encompass expression of SLC7A11, GPX4, FSP1, ACSL4, NRF2 pathway activation, and intratumoral labile iron content." (PMID 41301464, 2025). "SLC7A11 (also known as xCT), significantly upregulated in various human malignancies and crucial for tumor initiation, development, and drug resistance, exhibits a dual regulatory role by governing both ferroptosis and disulfidptosis." (PMID 40861466, 2025). "Studies using single‐cell RNA sequencing have indicated that ferroptosis‐related genes such as ALOX12 and SLC7A11 show differential expression patterns across distinct tumor regions, contributing to the heterogeneous response to FINs." (PMID 40919133, 2025).